PATE4 (prostate and testis expressed 4)
Description:
May modulate the function of nicotinic acetylcholine receptors. May enhance sperm motility.
Synonyms: PATE-B; FLJ41047
Tractability: Antibody: UniProt places it where antibodies can reach, with medium confidence; UniProt predicts a signal peptide or a membrane-spanning region; its Gene Ontology location is reachable by antibodies, with medium confidence.
Gene: Protein-coding gene on chromosome 11 (125,833,316 to 125,840,072, forward strand). Ensembl gene ENSG00000237353.
Subcellular location: Secreted; Cytoplasmic vesicle, secretory vesicle, acrosome
Gene Ontology:
Molecular function: acetylcholine receptor regulator activity
Biological process: regulation of neurotransmitter receptor activity
Cellular component: acrosomal vesicle; extracellular region
Genetic constraint (gnomAD): Loss-of-function variants: 13 observed, 8.96 expected, observed/expected ratio (o/e) 1.45, 90% interval 0.92 to 1.92. That is too few expected variants to judge how well the gene tolerates losing a copy. Missense variants: 127 observed, 119.1 expected, observed/expected ratio (o/e) 1.07, 90% interval 0.92 to 1.24. Synonymous variants: 47 observed, 40.88 expected, observed/expected ratio (o/e) 1.15, 90% interval 0.91 to 1.47.
Homologues: Orthologues: chimpanzee PATE4 (100% identical), macaque PATE4 (93% identical), mouse Pate4 (40% identical), rat Pate4b (38% identical). Paralogues in human: ACRV1 (29% identical), PATE1 (24% identical), PATE3 (23% identical), PATE2 (19% identical).
Diseases named in the same sentence as PATE4 in open-access papers:
PATE4 is named in the same sentence as 3 diseases in open-access papers, as found by Europe PMC text mining. Sharing a sentence is not in itself a finding about the gene and the disease. The quoted sentences say what the papers report.
male infertility (1 paper, 2016). The inability of the male to effect fertilization of an ovum after a specified period of unprotected intercourse. "Both PATE4 and AZGP1 being proteins secreted into the extracellular environment, they might thus constitute appealing targets for the non-invasive diagnosis of male infertility." (PMID 27695046, 2016).
prostate carcinoma (1 paper, 2024). A carcinoma that arises from epithelial cells of the prostate gland. "PATE4, which encodes prostate and testis expressed 4, has been found to be underexpressed in prostate cancer; however, how it contributes to prostate cancer remains unknown." (PMID 38173042, 2024).
varicocele (1 paper, 2015). A condition characterized by the dilated tortuous veins of the spermatic cord with a marked left-sided predominance. "The absence of PATE4 in varicocele patients emphasizes the role of PATE4 in enhancing sperm motility, the absence of which could cause the poor sperm motility in varicocele patients." (PMID 25890347, 2015). "PATE4 was uniquely expressed in the healthy fertile group and absent in varicocele patients." (PMID 25890347, 2015).